SP1 (Sp1 transcription factor)
Diseases named in the same sentence as SP1 in open-access papers (continued):
Sharing a sentence is not in itself a finding about the gene and the disease.
infection (continued). "Furthermore, injection into the lower leaf of Xanthi tobacco within Sp1 protein for 12 h significantly inhibited the infection of B. cinerea, indicating that W10-Sp1 activated systemic resistance of the host, including peach twigs, fruits and Xanthi tobacco." (PMID 36267189, 2022). "We found agreement between all samples in which a SARS-CoV-2-infection was identified via the detection of NCP-, RBD- and/or SP1-IgG in the Mikrogen® recomLine blot and those in which an infection was identified via the detection of IgG to SP1 in the Roche® ECLIA." (PMID 35951611, 2022). "Our data demonstrated that targeting miR-1224 in NK cells may be a novel strategy to potentiate immune defense in the periphery and prevent poststroke infection through a mechanism that depends on Sp1 signaling." (PMID 34118948, 2021). "Infection also induces cPLA2α transcription via transcriptional factors, such as nuclear factor κB (NF-κB), Krüppel-like factor, hypoxia-inducible factor (Hif), specificity protein 1 (Sp1), and c-Jun, that are well known to regulate immune cell activation." (PMID 34179001, 2021). "For instance, the observed expression changes of several transcriptional regulators including MIER1, which regulates the transcription of many SP1 target genes, may in part explain the predominantly observed decrease in protein expression on infection." (PMID 32591346, 2020). "Also, administration of specific inhibitors of c-Myc or SP-1 during infection in cells from both groups, will determine the regulatory roles of these transcription factors on CD147 and HDAC4 in epithelial cells." (PMID 30068332, 2018). "A related and testable hypothesis is that the three HIV subtypes (D, F and H) with mutations in Sp1 site III may demonstrate an increased propensity for latency and thus give rise to larger latent reservoirs relative to subtype B infection." (PMID 23874178, 2013). "Our previous studies have suggested that in vivo, as the infection cycle progresses and the level of capsid proteins in the nucleus becomes sufficiently high, they are recruited by Sp1 to ses, turning off the early and late promoters and forming the assembly nucleation center." (PMID 17712413, 2007). "In contrast, replacing the 2SP site with conserved SP1/SP3 binding sequences significantly reduced promoter activity, with a more pronounced reduction observed post-infection." (PMID 40362465, 2025). "Except for the 2SP site, mutations at the 1SP site (−262/−253bp), an adjacent upstream SP1/SP3 recognition site relative to the 2SP site, also showed a specific response to H37Ra infection, but with the opposite effect." (PMID 40362465, 2025). "By substituting the 2SP site with corresponding sequences from humans, pigs, and mice and predicting their respective affinities for SP1/SP3, we observed that a lower affinity of the 2SP site correlates with higher promoter activity following H37Ra infection." (PMID 40362465, 2025). "Subsequently, stable knockdown of SP1 in MGC803 and AGS cells were conducted by lentivirus-mediated shRNA infection." (PMID 38356702, 2024). "Infection of IAV induced ERS and activated IRE1/XBP1 signaling pathway to degrade SOD and Sp1 through the ERAD pathway." (PMID 37483299, 2023). "Specifically, the core-promoter exhibits 2 E-box motifs, TATA box and 3 Sp1 (I, II, III) binding sites while the core-enhancer domain exhibits at least 3 NF-kB binding sites for subtype C infection." (PMID 37307292, 2023). "During infection with the ΔhtrA mutant, CBX5 was activated and CLU, KLF5, SP1, TCF7L2 and UBE2I were inhibited." (PMID 37193047, 2022). "Other upstream regulators such as CLU, KLF5, SP1 and TCF7L2 that were inhibited by ΔhtrA mutant infection have also been previously shown to be involved in apoptosis regulation." (PMID 37193047, 2022).
infection (continued). "Specifically, on the one hand, the expression of TGFBRII was shown to be significantly decreased in BMECs by the infection of meningitic E. coli RS218, during which the transcription factor Sp1 mediated this TGFBRII downregulation." (PMID 34281571, 2021). "Recognition receptor genes, SP1 and SP7, were downregulated at 49 h post infection and then upregulated at 84 h, while CTL1 showed the opposite pattern." (PMID 33815150, 2021). "During PCV2 infection, however, PCV2 Rep promoted the binding activities of NF-κB p50 and Sp1 with the il10 promoter only at the later phase of PCV2 infection, since Rep proteins only expressed at the later phase of the infection." (PMID 31835539, 2019). "Here, we present data that RBP2 can be induced by Helicobactor Pylori CagA through AKT-Sp1 pathway and Sp1 directly binds to RBP2 promoter, contributing to its induction during infection." (PMID 25015565, 2014). "We first detected the expression levels of Sp1 and Sp3 in RAW264.7 cells following H37Ra infection." (PMID 40362465, 2025). "The results of RT-qPCR show that, under GMI1000 infection, the splicing ratios of RLPK.1/RLPK.2 and SP1.1/SP1.2 significantly increase, with RLPK.1/RLPK.2 approximately three-times higher and SP1.1/SP1.2 about twelve-times higher than in ΔhrcV-infected samples." (PMID 40006793, 2025). "Nonetheless, Sp1 is upregulated upon binding of the CMV cell surface proteins glycoprotein (g) B and hemoglobin (h) B to the cell receptors during the course of lytic infection." (PMID 40143226, 2025). "Our findings indicatethat interferon-γ inducible factor 16 acts as an antiviral factor inAAV2 infection and AAV2 vector-mediated cell transduction in animmune-modulatory independent way by interrupting the Sp1-dependent geneexpression from viral or vector genomes." (PMID 38837381, 2024). "To address the SP1-77 neutralization mechanism, we applied a lattice light sheet microscopy (LLSM) approach to monitor target cell infection by a chimeric vesicular stomatitis virus in which the coat glycoprotein was replaced by the SARS-CoV-2 (Wuhan strain) S protein (VSV-SARS-CoV-2)." (PMID 35951767, 2022). "Thus, to determine if T. denticola influences Sp1 expression in the PDL, hPDL cells were challenged with Td-WT and Td-CF522 bacteria at a multiplicity of infection of 50 for 2-hours followed by a 22-hour incubation period in media." (PMID 34255809, 2021). "Moreover, several TFs, such as NFKB1, p65, JUN, SP1 and STAT3, were demonstrated previously to be involved in the regulation of lung inflammation and immunity during pathogen infection or external stimulation." (PMID 32592597, 2020). "Overall this data implies that the TLR-activated host factors NFκB (RelA), SP1, RXR and members of the IRF family play a central role in activating the enhancer in infection and that these factors may form a functional network." (PMID 25856589, 2015). "It has recently been shown that some hypervirulent Sp1 mutants lacking the spxB gene and thereby producing less hydrogen peroxide were selected during infection because of higher resistance to early macrophage clearance." (PMID 26214695, 2015). "In the pathogen exposure treatments, high levels of infection were obtained for the GG4 clone when exposed to the Sp1 strain, but not when exposed to the Sp8 strain (Exp." (PMID 21550363, 2011). "However, SP1 overexpression exhibited similar activation ability (1.8-fold and 2.0-fold) regardless of infection status." (PMID 40362465, 2025). "These master regulators include EGR1, FOS, SRF, and SP1, and could be interesting targets for future studies, since they could switch on several pathways targeting the genes that are important to the successful alleviation of HPAI infection." (PMID 35205087, 2022).
infection (continued). "Moreover, silence of the thymine DNA glycosylase (TDG), a Rep-binding protein, significantly reduced the binding activities of NF-κB p50 and Sp1 with il10 promoter, resulting in the reduction of IL-10 production in PCV2-inoculated PAMs at the later phase of infection." (PMID 31835539, 2019). "We also observed enrichment of binding sites for the transcription factor SP1, which we had previously identified in networks built following PICV infection, and which showed differential DNA-binding activities between infection with attenuated and virulent viruses early during in vitro infection." (PMID 21994748, 2011). "This particular Sp1 site is involved in regulation of the human TNF gene in cells of the monocyte/macrophage lineage in response to MTb infection and to treatment with LPS but has no apparent role in TNF gene regulation in T cells activated by calcium influx or by T cell receptor ligands." (PMID 17637837, 2007). "SP1 demonstrated a greater ability to activate basal transcription, while only SP3, not SP1, specifically enhanced its ability to activate NRAMP1 expression after H37Ra infection." (PMID 40362465, 2025). "By contrast, infections were obtained for the GG13 clone after exposure to the Sp8 strain, but not to the Sp1 strain (Exp." (PMID 21550363, 2011). "In a MRC-5 lytic infection model, transient transfection with two individual JMJD3 siRNAs led to reduced accumulation of hCMV IE mRNAs (IE1 and Us3) and IE1 protein, but not cellular controls GAPDH and Sp1." (PMID 28407004, 2017).
cardiovascular diseases (13 papers, 2013 to 2026). "The arachidonate 5-lipoxygenase (ALOX5) specificity protein 1 (Sp1) promoter tandem repeat polymorphism is associated with enhanced cardiovascular disease (CVD) risk." (PMID 42141771, 2026). "Given its multifaceted involvement, SP1 holds promise for enhancing diagnostic and therapeutic strategies for cardiovascular diseases." (PMID 39062521, 2024). "More importantly, Sp1 has also been shown to be associated with the occurrence and progression of a variety of cardiovascular system diseases." (PMID 39252788, 2024). "Published literature in the field of cardiovascular diseases reports inhibition of Sp1, a transcription factor for CSE, by miR-22." (PMID 41583211, 2025). "This article discusses the molecular makeup, physiological role, and PTMs of Sp1 in controlling cardiovascular disease." (PMID 39252788, 2024). "The impact of Sp1 PTMs on cardiovascular disease is further explored in the subsequent discussion, particularly in relation to the regulation of Sp1 stability and transcriptional activity." (PMID 39252788, 2024). "Understanding Sp1 PTMs advances our knowledge of cell signaling pathways in controlling Sp1 stability during cardiovascular disease onset and progression." (PMID 39252788, 2024). "According to these results, Sp1 is a potentially novel therapeutic target for ACEIs in preventing cardiovascular disease." (PMID 39252788, 2024). "Numerous studies have confirmed Sp1’s significant regulatory role in the pathogenesis of cardiovascular disorders." (PMID 39252788, 2024). "From previous studies, we suspected that Sp1 and Sp3 played an important role in the pathogenesis of cardiovascular diseases." (PMID 37735515, 2023). "The transcription factors Sp1/Sp3 play important roles in various cardiovascular diseases and therefore have been a major research focus." (PMID 36759621, 2023). "A recent paper investigating H2S-microRNA crosstalk in cardiovascular diseases and estrogenic cardioprotection against oxidative stress, demonstrated that estrogen activates ERα, which binds to Sp1 increasing CSE production in murine cardiomyocytes." (PMID 29254196, 2017). "Thus, a thorough investigation into the PTMs of Sp1 and their impact on the development and advancement of cardiovascular diseases offers a fresh perspective on the molecular mechanisms underlying these conditions." (PMID 39252788, 2024). "Recent evidence suggests that Sp1’s phosphorylated state-especially notable in cardiovascular disease research-may be crucial in regulating several genes." (PMID 39252788, 2024). "Post-translational modifications of Sp1 in cardiovascular diseases." (PMID 39252788, 2024). "Sp1/Sp3 represents innovative therapeutic target for captopril to prevent cardiovascular diseases." (PMID 37735515, 2023). "Some of the master regulators identified in WAT in the present study (Jun, Fos, Rarα, Pparα, Stat1, Stat5, Sp1) were also reported to control liver lipid metabolism and/or the inflammatory responses of the liver in experimental diet-induced cardiovascular disease." (PMID 24086498, 2013).
neurodegenerative disease (12 papers, 2017 to 2025). A disorder of the central nervous system characterized by gradual and progressive loss of neural tissue and neurologic function. "SP1, a multifunctional zinc finger transcription factor that binds to GC‐rich motifs in DNA, is implicated in stress‐related apoptosis of neurons and the pathogenesis of a variety of degenerative diseases." (PMID 32562344, 2020). "In addition, many studies have proved the proinflammatory effects of SP1, which are quite common in neurodegenerative diseases." (PMID 34970121, 2021). "Specificity protein 1 (Sp1) is a transcription factor, the target genes of which include amyloid β precursor protein (APP), BACE1, Tau, and Htt, which all play vital roles in neurodegenerative diseases." (PMID 31049134, 2019).
kidney disease (7 papers, 2013 to 2025). "Sp1 is an essential transcriptional regulator for the antifibrotic protein follistatin and was identified as a profibrotic factor in kidney disease." (PMID 36457754, 2022). "Importantly, we established that Sp1, which has thus far been identified as a profibrotic factor in kidney disease, is a critical transcriptional regulator for the antifibrotic protein FST." (PMID 30995923, 2019). "We thus examined expression of Sp1 in ANG II-mediated kidney disease." (PMID 23301086, 2013). "Targeting SP1 or SP3 may exert positive effects on renal diseases." (PMID 39850832, 2025). "In the current review article, we mainly highlight the role of SP1 and SP3 in kidney diseases as the other members of SP family protein is less expressed in kidney tissue." (PMID 39850832, 2025). "Thus, therapeutically targeting enhanced activity of PI3K/PKCζ/Sp1 is not a viable option for the treatment of kidney disease due to potential unwanted profibrotic effects." (PMID 30995923, 2019).
inflammation (6 papers, 2013 to 2022). Aberrant reaction of the microcirculation characterized by movement of fluid and leukocytes from the blood into extravascular tissues. "SP1-TGF-β/Smad3-NFκB-dependent mechanisms have been found to lead to ANG II-mediated renal inflammation and fibrosis in mice." (PMID 36189232, 2022). "Since Sp1 activity is an endogenous anti-inflammatory mechanism, this result suggests that NF-κB activation can promotes lung inflammation by suppressing Sp1-mediated anti-inflammatory mechanisms." (PMID 26103469, 2015). "Since the Sp1 and NF-κB pathways are two major signaling pathways, crosstalk between the two pathways can be significant and may have major impacts on overall pathological process and on the magnitude of lung inflammation." (PMID 26103469, 2015). "This new finding suggests that enhanced ANG II-induced Sp1 pathway may be an additional mechanism by which mice lacking Smad7 were promoted ANG II-mediated renal inflammation and fibrosis." (PMID 23301086, 2013).
adenocarcinoma (4 papers, 2015 to 2025). A common cancer characterized by the presence of malignant glandular cells. "This evidence together with the reported observation that Smad3 can form transcriptional complexes with Sp1 to regulate gene expression, led us to focus our investigation on Sp1 as a candidate transcription factor in mediating TGFβ-induced PAR-1 upregulation in A549 adenocarcinoma cells." (PMID 27566553, 2016).
cardiac diseases (4 papers, 2022 to 2024). "Taken together, our results suggest that FB_sp2 may serve a crucial role in other cardiac diseases besides MI, and other subpopulations like FB_sp1 and FB_sp3 may also be associated with some specific cardiac diseases." (PMID 35252172, 2022). "Notably, SP1 was reportedly implicated in the development of cardiac diseases." (PMID 35048778, 2022). "Recent advances in both basic and clinical research have unveiled the additional roles of SP1 in the onset and progression of heart diseases." (PMID 39062521, 2024). "Consequently, SP1 influences the development of cardiac diseases by participating in pathological processes like inflammation, cell growth, angiogenesis, and fibrosis." (PMID 39062521, 2024).
colorectal (3 papers, 2015 to 2026). "Mechanistically, CYP1B1 activates the AKT/SP-1 signaling pathway to upregulate GPX4 expression, thereby modulating colorectal carcinogenesis and progression." (PMID 41493849, 2026).
bacterial infection (2 papers, 2007 to 2015). "Thus, there is a strong correlation between transcription factor binding at the upstream Sp1 site and transcriptional activation in response to bacterial infection but not to calcium influx among these primate TNF promoters." (PMID 17637837, 2007). "Also of interest is the presence in a subset of BAHD1-DMRs of binding sites for the transcription factor SP1, with which BAHD1 co-immunoprecipitates, as well as for STAT factors that may act in synergy with BAHD1 to repress immunity gene expression during a bacterial infection." (PMID 26648976, 2015).
immune disorders (1 paper, 2014). "Human hs1.2 has four different variants with unique binding sites for transcription factors (e.g. NF-kB and SP1) and shows variable allelic frequencies in populations with immune disorders." (PMID 25391515, 2014).
neurological disorders (1 paper, 2019). "Sp1 ubiquity and broad co-expression of p11 and TASK1 all along the CNS17,18, suggest the need for further investigation on this triad to ascertain feasible biomarkers for diverse psychiatric and neurological disorders." (PMID 31439839, 2019).
retinopathy (1 paper, 2020). "Our results showed that the expression pattern of SP1 paralleled that of LINGO‐1 in ONC‐injured RGCs, further implying that SP1 may regulate LINGO‐1 in retinopathy." (PMID 32562344, 2020).
SP1 also shares sentences with these, for which no sentence is quoted: preeclampsia (4 papers); bipolar disorder (3); colon adenocarcinoma (3); colorectal tumor (3); coronary heart disease (3); allergic disease (2); bacteremia (2); breast adenocarcinoma (2); dermatitis (2); hypertrophy (2); lung squamous cell carcinoma (2); neuropathies (2); psychiatric disorder (2); pulmonary hypertension (2); Acidosis (1); acute myocardial infarction (1); acute pancreatitis (1); alveolar rhabdomyosarcoma (1); amyotrophic lateral sclerosis (1); anaphylaxis (1); Aortic dissection (1); Arrhythmia (1); attention deficit-hyperactivity disorder (1); autoimmune hepatitis (1); B-cell lymphomas (1); benign tumors (1); brain cancer (1); brain disorder (1); Burkitt lymphoma (1); carotid atherosclerosis (1).
A further 78 diseases each share a sentence with SP1 in 1 paper.